HCG27 (HLA complex group 27)
Synonyms: bPG299F13.9; bCX101P6.9; bQB115I13.2; FLJ40123
Gene: Long non-coding RNA gene on chromosome 6 (31,197,715 to 31,211,696, forward strand). Ensembl gene ENSG00000206344.
Diseases named in the same sentence as HCG27 in open-access papers:
HCG27 is named in the same sentence as 11 diseases in open-access papers, as found by Europe PMC text mining. Sharing a sentence is not in itself a finding about the gene and the disease. The quoted sentences say what the papers report.
psoriasis (4 papers, 2008 to 2021). An autoimmune condition characterized by red, well-delineated plaques with silvery scales that are usually on the extensor surfaces and scalp. "Although HCG27 is reported to be a pseudo-gene, we observed a significant difference in expression levels between mild and severe CF individuals and the region including HCG27 is also a major susceptibility loci for psoriasis." (PMID 28846703, 2017). "rs9501077 is found in the long non-coding RNA (lncRNA) gene, HCG27 (HLA Complex Group 27), which has been linked to psoriasis, however the finding of a significant association with asthma for this SNP was not replicated in the UK Biobank data (UK Biobank p = 0.020)." (PMID 34669738, 2021). "But, there is limited evidence for HCG27 to be the primary susceptibility gene for psoriasis." (PMID 18369457, 2008). "SNP rs1265181 in HCG27 is the top association signals in a GWAS of psoriasis in Han Chinese population, while rs130065 in CCHCR1 has been consistently associated with psoriasis in multiple populations, and HCR1 protein expressed differently between lesional skin and normal skin." (PMID 22125590, 2011).
breast carcinoma (1 paper, 2020). "Constitutional genes with increased breast cancer relapse risk were claudin 15, WDFY2, golgin A4, DOCK4 while HCG27 and PLAC8L1 were among 18 signature signs not endorsed by prognostic index score." (PMID 33106505, 2020).
Cerebral ischemia (1 paper, 2025). Restriction of arterial blood supply to the brain associated with insufficient oxygenation to support the metabolic requirements of the tissue. "We explore the effect of improving cognitive dysfunction after cerebral ischemia–reperfusion (CI/R) by regulating HCG27." (PMID 40682202, 2025).
cerebrovascular disease (1 paper, 2025). "Silencing HCG27 can protect against cognitive dysfunction after cerebrovascular disease by targeting miR-27a-3p." (PMID 40682202, 2025).
depression (1 paper, 2024). "In previous GWAS and clinical studies, these genes have been associated with neurogenesis (WNT3), neurodevelopmental delays (QRICH1), addiction (HCG27), depression (CCDC71, CYP21A2), and other brain-related disorders." (PMID 39269986, 2024).
ischemic stroke (1 paper, 2025). A stroke disorder caused by obstruction of blood flow to the brain, due to thrombotic (local blood clot formation) or embolic (due to a blood clot or other material traveling from another site) event. "Furthermore, we will analyze serum and brain tissue samples from ischemic stroke patients to detect the expression levels of HCG27 and miR-27a-3p." (PMID 40682202, 2025). "In addition, competitive endogenous RNA network analysis revealed that HCG27 was differentially expressed in acute ischemic strokes and may correlate with inflammation." (PMID 40682202, 2025). "In addition, lncRNA HCG27 is differentially expressed in ischemic stroke." (PMID 40682202, 2025).
Stroke (1 paper, 2025). Sudden impairment of blood flow to a part of the brain due to occlusion or rupture of an artery to the brain. "Future research will explore whether HCG27/miR-27a-3p regulates known stroke-related pathways through transcriptomic and proteomic approaches, aiming to identify potential combinatorial therapeutic targets." (PMID 40682202, 2025).
HCG27 also shares sentences with these, for which no sentence is quoted: AIDS (1 paper); asthma (1); lymphoma (1); Neurodevelopmental delay (1).